CDK6 (cyclin dependent kinase 6)
Diseases named in the same sentence as CDK6 in open-access papers (continued):
Sharing a sentence is not in itself a finding about the gene and the disease.
malignant glioma (5 papers, 2012 to 2021). A grade III or grade IV glioma arising from the central nervous system. "Immunoblotting confirmed increased CDK6 protein expression in malignant gliomas consistent with the elevated transcript levels, and immunohistochemistry verified the graded distribution of the protein in the tumors." (PMID 23594394, 2013). "Specifically in the context of malignant glioma, these include NOTCH1, NOTCH2, MET, and CDK6." (PMID 22479456, 2012). "Furthermore, CDK6 is downregulated by over-expression of miR-495 in GBM cells, suggesting that miR-495 might play an important role in malignant glioma tumorigenesis." (PMID 23594394, 2013).
rhabdomyosarcoma (5 papers, 2019 to 2025). A rare aggressive malignant mesenchymal neoplasm arising from skeletal muscle. "Regarding another rare tumor, alveolar rhabdomyosarcomas (RMS), amplifications at 12q13q14 and 2p24 have been described, leading to the overexpression of CDK4 and CDK6, among other genes." (PMID 38275873, 2024).
small cell lung carcinoma (5 papers, 2015 to 2024). Small cell lung cancer (SCLC) is a highly aggressive malignant neoplasm, accounting for 10-15% of lung cancer cases, characterized byrapid growth, and early metastasis. "Meanwhile, the newest CDK4/CDK6 inhibitor, trilaciclib, is being studied in small cell lung cancer (SCLC) and triple-negative breast cancer (TNBC) in a bid to prevent chemotherapy-induced myelosuppression." (PMID 34361615, 2021).
stomach cancer (5 papers, 2015 to 2023). "Notably, CDK4 and CDK6 were significantly upregulated in gastric tumors than adjacent normal tissues and were dysregulated among GC patients." (PMID 36755269, 2023).
T-cell lymphoma (5 papers, 2013 to 2025). "For example, native CDK6 levels promote cell proliferation in T-cell lymphoma, yet forced overexpression of CDK6 protein inhibits cell proliferation by participating in positive transcriptional regulation of the tumor suppressor p16INK4a." (PMID 35463324, 2022). "In T cell lymphomas TCF3 exerts its tumor suppressing function by repression of proto-oncogenes MYC, CDK6 and by up-regulation of cell cycling inhibitor CDKN1A/p21, thereby leading to cell cycle arrest." (PMID 27166193, 2016). "The regulation of VEGF-A by CDK6 was not restricted to BCR-ABL+ cells, but was also observed in our T cell lymphoma model." (PMID 23948297, 2013).
acute leukemia (4 papers, 2019 to 2023). A clonal (malignant) hematopoietic disorder with an acute onset, affecting the bone marrow and the peripheral blood. "In acute leukemia patients, CDK6 over-expression has been frequently associated with KMT2A translocations, as it has been demonstrated that CDK6 is a direct target of KMT2A fusion proteins." (PMID 36770891, 2023). "Indeed, CDK6, expressed in hematopoietic cells, is a direct target of MLL fusion proteins often observed in acute leukemia and thus contributes to leukemogenesis." (PMID 34065376, 2021).
adrenocortical carcinoma (4 papers, 2017 to 2025). "Taken together, these data underline the impact of CDK4 and CDK6 inhibitors in treating adrenocortical carcinomas." (PMID 29283884, 2017). "In this study, we found that lncRNA ASB16-AS1 inhibits adrenocortical carcinoma cell cycle progression and cell proliferation by inhibiting CDK6 and IGFR expressions, which is mediated by RNA-binding protein HuR." (PMID 33219221, 2020). "We then found that IGF1R and CDK6 were up-regulated upon knockdown of ASB16-AS1 in adrenocortical carcinoma cells." (PMID 33219221, 2020). "Collectively, these data indicate that ASB16-AS1 regulates expression of IGF1R and CDK6 in adrenocortical carcinoma cells." (PMID 33219221, 2020). "We then found that IGF1R and CDK6 are regulated by ASB16-AS1 in adrenocortical carcinoma cells by transcriptome RNA sequencing." (PMID 33219221, 2020). "We knocked down the expression of HuR in adrenocortical carcinoma cells and the results showed that inhibition of HuR reduced the stability of CDK6 and IGF1R mRNAs." (PMID 33219221, 2020). "Our study found that ASB16-AS1 inhibits IGF1R and CDK6 in adrenocortical carcinoma, modulating of their levels may be developed to treat this type of carcinoma." (PMID 33219221, 2020). "The results turned out that knock-down of BTRC abolished the down-regulation of HuR, CDK6, and IGF1R expression upon enhanced expression of ASB16-AS1 in adrenocortical carcinoma cells." (PMID 33219221, 2020).
Arthritis (4 papers, 2018 to 2025). Inflammation of a joint. "Functional enrichment further supported that the primed genes are heavily involved in inflammatory response, arthritis-promoting functions (Ccl2, Cxcl5, Sphk1) and, interestingly, Wnt pathway (Bmp2, Rspo3, Cd44) and stem cell differentiation (Sox5, Nrp2, Cdk6)." (PMID 35879783, 2022).
atherosclerosis (4 papers, 2021 to 2024). A disease characterized by the build-up of fatty material and calcium deposition in the arterial wall resulting in partial or complete occlusion of the arterial lumen. "CDK6, mainly discussed as an anti-cancer drug target, has been implicated in pulmonary arterial hypertension, loss of its activity can lead to heart failure and is a major regulator of atherosclerosis." (PMID 38326862, 2024). "CDK6 has been identified as a key regulator of atherosclerosis for CDK6 knockdown can suppress proliferation of HASMC and HUASMC." (PMID 35449099, 2022). "Using the GSE6088 database, the results showed CDK6 expression in atherosclerosis was induced by 1.44-fold compared to normal samples." (PMID 33659023, 2021). "In addition, the depth of mechanism research is not sufficient, we only performed bioinformatic assay and in vitro functional experiments revealing the signaling axis circHIPK3/miR-637/CDK6 in atherosclerosis." (PMID 33659023, 2021). "First, we screed out DEGs according to GSE6088 database, the other significantly DEGs except CDK6 may also have important regulatory effects on atherosclerosis, and needs to be further studied." (PMID 33659023, 2021). "Also, we identified CDK6 as a key regulator of atherosclerosis." (PMID 33659023, 2021).
B cell lymphocytic leukemias (4 papers, 2013 to 2022). "Chromosomal translocations within the CDK6 promoter that lead to CDK6 overexpression were also described in splenic marginal zone lymphomas and B-cell lymphocytic leukemias." (PMID 36051751, 2022). "For example, CDK6 promoter related chromosomal translocation leads to CDK6 overexpression, which has been reported in B cell lymphocytic leukemias and splenic marginal zone lymphoma." (PMID 28286417, 2017).
cognitive decline (4 papers, 2021 to 2024). "It plays a certain role in upstream regulation and may prevent astrocyte aging in AD models via the CDK6 signaling pathway, such that cognitive decline can be slowed down." (PMID 37549144, 2023).
Ewing sarcoma (4 papers, 2014 to 2021). A small round cell tumor that lacks morphologic, immunohistochemical, and electron microscopic evidence of neuroectodermal differentiation. "Since CDK6 overexpression could result in resistance to CDK6 inhibitors, additional copies of CDK6 were introduced in A-673, an Ewing’s sarcoma cell line." (PMID 34771669, 2021). "Previous studies also indicated that knock-down of CDK6 could inhibit cell invasion and migration in gastric and Ewing¿s Sarcoma." (PMID 25178497, 2014).
head and neck cancer (4 papers, 2014 to 2021). A primary or metastatic malignant neoplasm affecting the head and neck. "Past studies have shown that cyclin-dependent kinase 4 and 6 (CDK4 and CDK6) are generally overexpressed in various tumor cells and related to the increase of cyclin A in head and neck carcinomas." (PMID 33921647, 2021).
metastatic melanoma (4 papers, 2018 to 2025). A melanoma that has spread from its primary site to another anatomic site. "High miR-200a and, consequently, low CDK6 expression were associated with resistance to palbociclib in metastatic melanoma." (PMID 34439268, 2021). "Inversely, metastatic melanoma cell lines with low miR-200a and high CDK6 expression were more susceptible to CDK4/6 inhibition." (PMID 34439268, 2021). "MiR-200a has been proven to inhibit CDK6 expression in metastatic melanoma cells, which is an important factor promoting tumour development." (PMID 36522613, 2022). "Critically, FRA1 directly activates AXL, CDK6, and FSCN1, which are upregulated in metastatic melanoma and correlate with poor patient outcomes." (PMID 41286309, 2025). "miR-200a negatively regulated CDK6 but not CDK4 expression in metastatic melanoma." (PMID 34439268, 2021).
myeloid leukemia (4 papers, 2021 to 2025). A clonal proliferation of myeloid cells and their precursors in the bone marrow, peripheral blood, and spleen. "To confirm the role of CDK6 in granule formation in human neutrophils, we used a human myeloid leukemia cell line (PLB-985), which can be differentiated into a neutrophil-like state." (PMID 40948552, 2025). "However, HOXA9 regarded as the “switch” of cell proliferation in the process of myeloid leukemia, which can promote the expression of CDK6, CyclinD1 gene and telomerase RNA by triggering pleiotropic oncogenes Myc and Myb, and provide necessary cofactors to maintain the rapid proliferation of cells." (PMID 38605318, 2024).
pancreatic ductal adenocarcinoma (4 papers, 2022 to 2023). An infiltrating adenocarcinoma that arises from the epithelial cells of the pancreas. "The small molecule inhibitors targeting CDK4 and CDK6 recuperate the impaired tumor suppression function induced by p16INK4A mutation, which revives the tumor growth in pancreatic ductal adenocarcinoma (PDAC)." (PMID 37390335, 2023).
prostate tumor (4 papers, 2013 to 2025). "Taken together our results suggest that miR-105 inhibits prostate tumour cell growth in part via its ability to downregulate the expression of the important cell cycle regulator CDK6." (PMID 23950948, 2013). "miR-105 inhibited prostate tumor growth by suppressing CDK6 levels." (PMID 31772674, 2019). "Also, the inverse relationship between the CDK6 and miR-105 expression levels we observed between PrEC and the prostate tumour cell lines, together with the increase in Cdk6 expression in PrEC transfected with miR-105 hairpin inhibitors lends further support to our hypothesis." (PMID 23950948, 2013). "Additionally, we observed significantly reduced mRNA expression levels of CCND1, p15INK4b, and RB in prostate tumor tissues compared to BPH tissues, while the expression levels of CDK4, CDK6, and p16INK4a remained unaltered." (PMID 40304827, 2025). "While for prognosis by using serum PSA levels and CDK6, TNRC6B, and AGO1 expression in prostate tumour tissue, the CART chart showed that a patient with PSA values ≤ 7.65 ng/ml, will harbour a high-risk PCa if the relative expression level of TNRC6B in PCa tissue is ≤ 5.618 (27%)." (PMID 37978493, 2023). "We checked the expression levels of CDK6, TNRC6B, AGO1, AGO3, and TNRC6A in PCa tissues, based on data from 465 prostate tumour samples obtained from TCGA-PRAD database, and stratified according to the 2014 ISUP-GG into low-risk (ISUP I and II) and high-risk (ISUP III, IV, and V)." (PMID 37978493, 2023).
renal carcinoma (4 papers, 2019 to 2026). A carcinoma arising from the epithelium of the renal parenchyma or the renal pelvis. "Furthermore, the let-7 family targets cell cycle control proteins such as CDK1, CDK 2, CDK6 and cyclin B1 in various tumours including renal cancer cells." (PMID 36076967, 2022).
rheumatoid arthritis (4 papers, 2011 to 2025). A chronic, systemic autoimmune disorder characterized by inflammation in the synovial membranes and articular surfaces. "Other polymorphisms within the CDK6 gene have been associated with susceptibility to rheumatoid arthritis and height." (PMID 21738479, 2011). "Additionally, SNPs in CDK6 are associated with rheumatoid arthritis." (PMID 40948552, 2025).
skin tumor (4 papers, 2014 to 2022). "Reduced cdk6 levels have also been observed in some pancreatic endocrine tumors as compared to normal tissue and cdk6 overexpression resulted in decreased skin tumor development in a transgenic mouse model." (PMID 24848372, 2014). "ShRNA knockdown of Cdk6 expression does not affect proliferation of Cdkn2ab-deficient MEFs and skin tumour cell lines under adherent conditions (data not shown) but does reduce the anchorage-independent colony outgrowth, which correlates with the extent of knockdown." (PMID 30926782, 2019). "Overexpression of CDK6 by retroviral transduction results in very efficient soft agar colony outgrowth both of skin tumour cell lines, with or without inactivation of the endogenous Wnt7b allele, and Cdkn2ab KO MEFs." (PMID 30926782, 2019).
Stroke (4 papers, 2016 to 2023). Sudden impairment of blood flow to a part of the brain due to occlusion or rupture of an artery to the brain. "Five were the targetgenes of let-7 (ESM1, VIM, CDK6, NRAS, and KRAS), 3 of which (ESM1, VIM, and CDK6) were correlated with stroke based on published literatures." (PMID 26830013, 2016). "Although the rest of 16 causal genes identified by the integrative analysis were only replicated in one or two analyses, some of them (e.g. ALDH2, CDK6, HDAC9, and SLC44A2) were previously reported linked to stroke, which also demonstrate the reliability of our integrative analysis in a way." (PMID 35449099, 2022). "In addition, the genome-wide significant stroke risk locus rs7974266 was upstream of differentially expressed gene PTPN11, rs12539561 was downstream of differentially expressed gene PIK3CG, and the 3-prime UTR variant rs42035 was downstream of differentially expressed outcome gene CDK6." (PMID 36691064, 2023).
T-cell leukemia (4 papers, 2014 to 2023). A malignant disease of the T-lymphocytes in the bone marrow, thymus, and/or blood. "Pimozide, an inhibitor of USP1, results in the arrest of adult T-cell leukemia cells in the G1 phase, leading to the accumulation of p21 and p27 and reduction in the protein levels of cyclin D2, cyclin E, CDK2, CDK4, and CDK6." (PMID 36357365, 2022).
adenoma (3 papers, 2019 to 2024). A neoplasm arising from the epithelium. "USP8-mutated adenomas showed higher level of POMC, CDC25A, MAPK4 but lower level of CCND2, CDK6, CDKN1B than USP8-wild-type tumors." (PMID 38862897, 2024). "It has been reported that the CDK6 expression increases from non-neoplastic mucosa through adenoma to submucosal invasive carcinoma to regulate the progression and metastasis of CRC47." (PMID 30655588, 2019).
B-cell lymphomas (3 papers, 2013 to 2025). "A parallel connection has been identified between miR-29 family and CDK6, interaction on which reside the miR-29-antiproliferative effects reported in B-cell lymphomas." (PMID 26496024, 2016).
brain cancer (3 papers, 2021 to 2022). A primary or metastatic malignant neoplasm affecting the brain. "GLR2007 was also shown to inhibit the enzymatic activity of CDK4 and CDK6, and induce G1 arrest in cell line U87-MG, a model of GBM brain cancer." (PMID 36033522, 2022). "One example is a CDKN2A deletion that sensitizes brain cancer cells to palbociclib (a CDK4/6 inhibitor) and to knockouts in CDK4 and CDK6 genes." (PMID 35614096, 2022).
Burkitt lymphoma (3 papers, 2013 to 2021). A rare form of malignant mature B-cell non-Hodgkin lymphoma. "Similarly, cyclin D3 and CDK6 were essential for development of T-cell leukemia and Burkitt lymphoma." (PMID 26295265, 2015).
cardiac hypertrophy (3 papers, 2014 to 2023). "Hypertrophic rat cardiomyocytes transfected with miR-1 mimics or CDK6 siRNA inhibit activation of the CDK6-Rb pathway, which is an important pathway in the regulation of cell cycle progression contributing to cardiac hypertrophy." (PMID 31547607, 2019). "MicroRNA-1 was also reported to be involved in the regulation of CDK6 mediated cardiac hypertrophy." (PMID 37829282, 2023).
cervical squamous cell carcinoma (3 papers, 2019 to 2022). A squamous cell carcinoma arising from the cervical epithelium. "For example, lncRNA DCST1-AS1 induces CDK6 in cervical squamous cell carcinoma via sponging miR-107." (PMID 34414241, 2021).
cholangiocarcinoma (3 papers, 2015 to 2023). A carcinoma that arises from the intrahepatic biliary tree (intrahepatic cholangiocarcinoma) or from the junction, or adjacent to the junction, of the right and left hepatic ducts (hilar cholangiocarcinoma). "Induction of G0/G1 cell cycle arrest in cholangiocarcinoma cells by vitamin D analogues is mediated by upregulation of p27 and downregulation of CDK4, CDK6, and cyclin D3." (PMID 37561808, 2023). "In cholangiocarcinoma cells, PTK7 depletion affected the level of cell-cycle related proteins, increasing Cdk2, Cdk4, Cdk6, and cyclin D1 and decreasing p16, p21, and p27, whereas it increased mitochondrial-dependent apoptosis." (PMID 25962058, 2015).
chronic myeloid leukemia (3 papers, 2015 to 2025).
Cirrhosis (3 papers, 2023 to 2025). A chronic disorder of the liver in which liver tissue becomes scarred and is partially replaced by regenerative nodules and fibrotic tissue resulting in loss of liver function.
colitis (3 papers, 2020 to 2023). Inflammation of the colon. "Cdk6 was selected for validation based on its involvement in inflammatory signaling and reported association with ulcerative colitis and colitis-associated dysplasia." (PMID 36361810, 2022). "Downregulation of miR-1 and corresponding upregulation of Cdk6 were identified in vivo as early events in the formation of colitis-associated dysplasia; alterations that may contribute to progression to CAC." (PMID 36361810, 2022). "In this study, exogenous let-7a-5p was shown to alleviate colitis through inflammatory response and cell cycle-related Cdk6 gene regulation." (PMID 37966243, 2023). "In this study, we documented that the expression of genes involved in cell cycle regulation was downregulated in the intestine of mice with colitis upon the administration of EVs through the suppression of CDK6/NF-κB signaling via transcriptomic analysis." (PMID 37966243, 2023). "The observed upregulation of Cdk6 in colonic dysplasias from mice with AOM/DSS-induced colitis, as compared to the surrounding inflamed mucosa, is consistent with clinical observations of altered CKD6 expression in patients with UC." (PMID 36361810, 2022). "Additionally, the bta-let-7a-5p, one of the most abundant microRNAs in bovine colostrum-derived EVs, alleviated the indications of colitis in mice by modulating their intestinal immunity and by regulating the cell cycle-related target gene Cdk6." (PMID 37966243, 2023).
colorectal adenoma (3 papers, 2021 to 2022). An adenoma that arises from the colon or rectum. "For example, miR-320 family is reported to be down-regulated in colorectal adenoma and repress cell proliferation by targeting CDK6." (PMID 35799265, 2022). "MiR-320 family members, including miR-320c, are low expressed in colorectal adenoma and influences cell proliferation through targeting CDK6." (PMID 35902921, 2022). "The hsa-miR-320 family, particularly hsa-miR-320e, is downregulated in colorectal adenoma and affects colorectal tumor proliferation by targeting CDK6." (PMID 34603447, 2021).